HOTAIR (HOX transcript antisense RNA)
Diseases named in the same sentence as HOTAIR in open-access papers (continued):
Sharing a sentence is not in itself a finding about the gene and the disease.
breast cancer (continued). "A recent study analyzed the in situ expression of HOTAIR in breast cancer patients and showed that a high expression of HOTAIR in tumor tissue is closely related to lymph node metastasis." (PMID 36233075, 2022). "A variety of evidence implicates HOTAIR as a key epigenetic regulator of breast cancer metastasis, but the details of the regulatory mechanism are unclear." (PMID 36579891, 2022). "Within breast cancer, HOTAIR has been found to be several hundred-fold more highly expressed in metastatic breast tumors and primary breast tumors destined to metastasize." (PMID 36579891, 2022). "HOTAIR overexpression in primary breast cancers is a significant and independent predictor of subsequent metastasis and death across multiple independent cohorts." (PMID 36579891, 2022). "Based on the important role of HOTAIR in breast cancer progression, a recent review summarized the potentially promising therapeutic function of HOTAIR in breast cancer." (PMID 36233075, 2022). "In brief, we conclude that breast cancer cells with elevated HOTAIR require persistent and sustained HOTAIR overexpression to retain a highly invasive and metastatic phenotype." (PMID 36579891, 2022). "This suggests that other m6A sites within HOTAIR mediate its high expression levels in breast cancer cells." (PMID 36441764, 2022). "HOTAIR can also promote the proliferation, migration, invasion and apoptosis of breast cancer cells by regulating miR-20a-5p/HMGA2 axis." (PMID 35093153, 2022). "We show that sustained high levels of HOTAIR over time increased breast metastatic capacity and invasiveness in breast cancer cells, promoting migration and subsequent metastasis to the lung." (PMID 36579891, 2022). "Studies have shown that HOTAIR can down-regulate miR-34a to promote the occurrence and development of tumors in breast cancer, gastric cancer and other tumors." (PMID 35093153, 2022). "Our results also suggest that targeting overexpressed HOTAIR transcript can potentially serve as a therapeutic strategy in breast cancer patients to limit metastatic progression." (PMID 36579891, 2022). "NF-κB was found to be involved in the maintenance of the CSC population in breast cancer, but the precise mechanisms that how HOTAIR is involved in this pathway still needs to be further elucidated." (PMID 36273585, 2022). "Human breast cancer cells which highly overexpress HOTAIR also display more metastatic and invasive properties compared to control cells." (PMID 36579891, 2022). "The well-studied LncRNA, HOX transcript antisense intergenic RNA (HOTAIR), was detected in sEVs derived from breast cancer patients, and the expression level of HOTAIR was positively correlated with HER2 in tumor tissues." (PMID 36212432, 2022). "Together, these results indicate that m6A methylation of HOTAIR, particularly at A783, occur in breast cancer cells and is dependent on the METTL3/14 complex." (PMID 36441764, 2022). "HOTAIR uses miR-The 206/TBX3 axis maintains the stemness of ovarian cancer stem cells and HOTAIR regulates the proliferation of breast cancer cells through the miR-206-mediated BCL-W signaling pathway." (PMID 36115953, 2022). "HSPA1A is a chaperone overexpressed in a large variety of tumor lines, including breast cancer, and its expression exhibited a positive correlation with that of HOTAIR in irradiated breast cancer cells." (PMID 34804940, 2021). "These scholars also convinced that HOTAIR overexpression in patients with breast cancer was an important predictor of metastasis and poor prognosis." (PMID 33473276, 2021). "Power analysis was carried out to assess the diagnostic value of PVT1, HOTAIR, NEAT1, MALAT1, PAI-1, and OPN in breast cancer." (PMID 33670447, 2021). "The precise implication of PVT1/PAI-1 and MALAT1, NEAT1/OPN/HOTAIR networks in breast cancer development is still unclear." (PMID 33670447, 2021).
breast cancer (continued). "Overexpression of HOTAIR in breast cancer cells increased invasiveness of these cells in a polycomb repressive complex 2 (PRC2)-dependent manner by reprogramming the polycomb binding profile similar to embryonic fibroblast." (PMID 34946977, 2021). "In the univariate analysis, serum levels of PVT1, HOTAIR, PAI-1, and OPN were found to be significant predictors associated with breast cancer risk." (PMID 33670447, 2021). "In breast cancer cells, the HOTAIR level is decreased following Ras homolog gene family member C (RhoC) knockdown via siRNA transfection, and Rho-associated protein kinase (ROCK) works as the intermediate effector." (PMID 34073224, 2021). "In this review, we summarize the recent advances of HOTAIR in breast cancer, in the hope of providing novel approaches to treating breast cancer." (PMID 34073224, 2021). "It is noticed that HOTAIR is upregulated in breast cancer tissues, while another lncRNA, downregulated in hepatocellular carcinoma (DRHC), is actually downregulated." (PMID 34073224, 2021). "Here, we have summarized the induction of HOTAIR in breast cancer and its impacts on cell proliferation, migration, apoptosis, and therapeutic resistance, as well as elucidating the underlying mechanisms." (PMID 34073224, 2021). "Alternatively, HOTAIR induces heat shock protein family A member 1A (HSPA1A) expression, a stress-associated protein, which endows radioresistance in breast cancer." (PMID 34073224, 2021). "Serum levels of PVT1, HOTAIR, PAI-1, and OPN were found to have diagnostic powers of 98%, 90%, 80%, and 88% in discriminating breast cancer from the healthy control." (PMID 33670447, 2021). "Apart from breast cancer cells, HOTAIR can also be induced by CAF, a pivotal component in the tumor microenvironment." (PMID 34073224, 2021). "HOTAIR is significant for maintaining breast cancer cell stemness and driving other malignant potentials." (PMID 34073224, 2021). "Overall, these findings highlighted that CAFs secreted TGFβ1 which triggered HOTAIR upregulation in breast cancer cells." (PMID 33511320, 2021). "Comparing breast cancer with fibroadenoma patients, HOTAIR expression levels were significantly higher, whereas NEAT1 expression levels were significantly lower in the breast cancer patients than in the fibroadenoma patients at p < 0.0001." (PMID 33670447, 2021). "The aim of this study was to characterize the phenotypic effects and signaling pathways modulated by HOTAIR in early-stage breast cancer progression." (PMID 34869037, 2021). "It was reported that CAF-secreted TGF-β1 can effectively stimulate HOTAIR expression in breast cancer cells by activating the TGF-β/Smad pathway." (PMID 34073224, 2021). "This review aims to provide new insights into investigations between HOTAIR and breast cancer development and inspire new methods for studying the association in depth." (PMID 34073224, 2021). "Early studies highlighted that the aberrant expression of HOTAIR in human tumors have been detected in breast cancer (BC) patients." (PMID 34576322, 2021). "At exploration stage (2010–2013), since the lncRNA HOTAIR had been proven to promote breast cancer metastasis by participating in chromatin remodeling, researchers paid a lot of rising attention on lncRNAs." (PMID 35047004, 2021). "HOTAIR expression positively correlates with malignant transformation and a poor outcome of several types of cancer as colorectal cancer, breast cancer, ovarian cancer, pancreatic cancer, and gastrointestinal tumors." (PMID 33670447, 2021). "In breast cancer, aberrant HOTAIR expression is responsible for advanced tumor progression by regulating multifarious signaling pathways." (PMID 34073224, 2021).
breast cancer (continued). "Calycosin is more effective in inhibiting breast cancer growth in comparison with genistein, through its regulation of Akt signaling pathways and HOTAIR expression." (PMID 34462889, 2021). "Elevated HOTAIR levels in breast cancer cells can facilitate HMGA2 expression by targeting and arresting miR-20a-5p levels, which ultimately contributes to cell proliferation and survival." (PMID 34073224, 2021). "Recently, metformin was reported to diminish cell viability by targeting HOTAIR in breast cancer cells." (PMID 34073224, 2021). "TGFβ1-mediated activation of SMAD2/3/4 induced transcriptional upregulation of HOTAIR in breast cancer cells." (PMID 33511320, 2021). "Further research into non-coding RNA has revealed that HOTAIR (HOX transcript antisense intergenic RNA) promotes breast cancer development." (PMID 34768930, 2021). "Overexpression of HOTAIR was correlated with metastasis and poor prognosis of various cancers, including breast cancer." (PMID 34946977, 2021). "HOTAIR overexpression is thought to be related to oestrogen response elements in its promoter, and E2 induces HOTAIR expression in breast cancer." (PMID 34651424, 2021). "HOTAIR has been shown to modulate critical molecular pathways related to breast cancer development and progression such as autophagy, epithelial mesenchymal transition (EMT), and drug resistance." (PMID 34869037, 2021). "In cancer stem cells originating from breast cancer, HOTAIR can also physically engage with the promoter region to mute a tumor suppressor microRNA (miR34a)." (PMID 34768930, 2021). "Increased HOTAIR levels can either be detected from tumoral tissues or serum samples, and its roles of being biomarker for the diagnosis and prognosis of breast cancer have been gradually recognized." (PMID 34073224, 2021). "Since its identification in breast cancer, HOTAIR overexpression has been reported in almost all solid tumor sites." (PMID 34869037, 2021). "The significance of serum PVT1, HOTAIR, NEAT1, MALAT1, PAI-1, and OPN levels as potential diagnostic biomarkers for breast cancer was assessed using a ROC curve." (PMID 33670447, 2021). "As HOTAIR is constantly overexpressed in breast cancer and plays broad roles in leading to deterioration, it is thus proposed as an ideal drug target." (PMID 34073224, 2021). "The role of HOTAIR in the development and progression of cancer has been described in breast cancer and HCC." (PMID 34200849, 2021). "We observed that the serum expression level of HOTAIR was significantly higher in the breast cancer patients compared to the fibroadenoma patients and the control subjects." (PMID 33670447, 2021). "STAT3 is a component of another important pathway that plays a role in inflammation during breast cancer progression, and several lncRNAs (e.g., HOTAIR and Lnc-BM) participate in this process." (PMID 34123857, 2021). "Here we characterized for the first time the phenotypic and molecular effects of HOTAIR overexpression in non-invasive breast cancer models." (PMID 34869037, 2021). "In this study, we analyzed the serum expression levels of lncRNAs PVT1, HOTAIR, NEAT1, and MALAT1, and their associated proteins, PAI-1, and OPN, in breast cancer patients compared to fibroadenoma patients and healthy subjects." (PMID 33670447, 2021). "Down-regulation of HOTAIR leads to radiosensitivity of breast cancer cells, induction of DNA damage, cell cycle arrest and apoptosis by recruiting miR-218." (PMID 32245498, 2020). "In breast cancer, HOTAIR was shown to promote invasion and metastasis by sponging miR-601, which consequently downregulated its target, ZEB1." (PMID 33375038, 2020). "Considering the critical role of HOTAIR in promoting breast cancer development, through different mechanisms of action, we further discuss the potential relationship of HOTAIR with response to different combinational therapeutic agents, in the next section." (PMID 32245498, 2020).
breast cancer (continued). "The abnormally expressed HOTAIR is closely related to the occurrence of various malignant tumors, including breast cancer, colorectal cancer, lung cancer, and gastric cancer." (PMID 33102210, 2020). "Increasing evidence indicates that the STAT3 pathway plays an important role in breast cancer metastasis, and several lncRNAs (e.g., HOTAIR and Lnc-BM) participate in this process." (PMID 32929060, 2020). "The metastatic potential of breast cancer can be limited by preventing the interaction of HOTAIR with PRC2 or LSD1 complexes using small molecule inhibitors." (PMID 31713618, 2020). "Collectively, the TGF-β/HOTAIR axis controls breast cancer development and metastasis by facilitating communication between CAFs and breast cancer cells in the tumor microenvironment." (PMID 33050576, 2020). "In breast cancer cell lines, the overexpression of HOTAIR enhances the cell colony formation, while its down-regulation reduces invasiveness of cancer cells in vitro." (PMID 33346222, 2020). "Considering diverse functions of HOTAIR, we briefly discuss some important mechanisms whereby this lincRNA contributes to breast cancer progression." (PMID 32245498, 2020). "For example, DSCAM-AS1 mediates tumor progression and tamoxifen resistance and HOTAIR reprograms the polycomb repressive complex binding pattern in breast cancer." (PMID 32190687, 2020). "Curiously, evidences emphasize the crucial role of HOTAIR overexpression in breast cancer radioresistance through EMT induction." (PMID 32245498, 2020). "HOTAIR is a kind of lncRNA that is found in human fibroblasts and is transcribed in antisense, and its expression is abnormally elevated in breast cancer and its metastases." (PMID 32390766, 2020). "In several malignancies including breast cancer, evidences demonstrated intermediating oncogenic role of HOTAIR, on the benefit of c-Myc oncogenic pathway activity." (PMID 32245498, 2020). "A positive regulation of HMGA2 was observed by activity of HOTAIR, as ceRNA for miR-20a-5p in breast cancer cells." (PMID 32245498, 2020). "An early study showed that HOTAIR was highly expressed in metastatic breast cancer tissues and promoted breast cancer lung metastasis." (PMID 32929060, 2020). "There are three studies in head and neck squamous cell carcinoma 33, ovarian cancer 34, breast cancer 35 but CRC focusing on the repressing role of HOTAIR to sponge miR-206." (PMID 32489462, 2020). "For instance, the upregulation of HOTAIR confers a resistance to tamoxifen, a conventional therapeutic for breast cancer patients, and is therefore a potential target for reversing chemoresistance." (PMID 33291485, 2020). "The expression of HOTAIR was analyzed in breast cancer samples and discovered that the high expression of HOTAIR facilitates metastasis and death." (PMID 33346222, 2020). "Apparently, further research is demanded to elucidate the roles and precise actions of HOTAIR in the occurrence, development, and progression of breast cancer metastasis." (PMID 32929060, 2020). "As previously indicated, HOTAIR activity directly fosters ER signalling in ER+ breast cancer cells to develop invasiveness and metastasis." (PMID 32245498, 2020). "For example, in breast cancer, HOTAIR downregulates HOXD10 favouring the invasive and metastatic behaviour." (PMID 33375038, 2020). "For example, expression dysregulation of HOTAIR has been observed in 42 human diseases, such as breast cancer, ovarian cancer, hepatocellular carcinoma, lung cancer, and atherosclerosis." (PMID 31713618, 2020).
breast cancer (continued). "The expression of HOTAIR results in increased invasion of breast cancer cells, which is closely related to the progression of breast cancer, thus leading to decreased survival and poor prognosis." (PMID 32390766, 2020). "To initiate the study of HOTAIR in breast cancer cells, we first analyzed its expression using data from The Cancer Genome Atlas (TCGA) database using cBioPortal." (PMID 32466537, 2020). "Previous studies have found that HOTAIR can be used as a critical marker for the diagnosis and prognosis of breast cancer." (PMID 33145980, 2020). "Unexpectedly, they found that the DNA of HOTAIR in serum is a novel biomarker for breast cancer to distinguish breast cancer patients from healthy individuals." (PMID 32929060, 2020). "In breast cancer cells, CAFs induced metastasis by enhancing the expression of HOTAIR transcriptionally, of which the promoter was bound with SMAD2/3/4." (PMID 33050642, 2020). "HOTAIR reprograms neuroendocrine differentiation of prostate cancer, and its overexpression increases H3K27me and metastatic potential of breast cancer cells." (PMID 33384663, 2020). "HOTAIR is the main upregulated lncRNA in tamoxifen-resistant breast cancer and it is able to interact with ER, repressing it, but enhancing its transcriptional activity also in the absence of ligand." (PMID 32397382, 2020). "Curiously, evidences have emphasised the crucial role of HOTAIR in cancer cell proliferation and metastasis as well as maintenance of breast cancer stem cells (bCSCs) and EMT." (PMID 32245498, 2020). "HOTAIR is also highly expressed in the CSCs obtained from two breast cancer cell lines: MCF-7 and MB-231, regulating self-renewal, proliferation, colony formation and migration by inhibiting miR-34a and subsequently up-regulating SOX2." (PMID 32245498, 2020). "Congruently, forced inhibition of HOTAIR in cells resulted in augmented miR-204 levels in breast cancer cells." (PMID 32466537, 2020). "This suggests potential correlation of HOTAIR and ERβ in breast cancer and subsequently downstream molecules, miR-138/204/217 and miR-200c, in breast cancer, although, it still remains to be investigated." (PMID 32245498, 2020). "Here, we provide experimental evidences suggesting that HOTAIR has a relevant function in hypoxia-induced vasculogenic mimicry and cell migration in breast cancer cells." (PMID 32466537, 2020). "In breast cancer cells, studies demonstrated relation of HOTAIR expression level with metastasis free survival and enhancing rim fraction (ERF) radiogenomics score." (PMID 32245498, 2020). "We subsequently summarize the potential role of HOTAIR overexpression on different processes of breast cancer development." (PMID 32245498, 2020). "First, we found that HOTAIR levels were significantly increased after 48 h hypoxia relative to normoxia in breast cancer cell lines, indicating a functional link between hypoxia and HOTAIR functions." (PMID 32466537, 2020). "For example, a siRNA-mediated HOTAIR degradation suggested a therapeutic role of HOTAIR inhibition, since its negative regulation reduced tumor cells dissemination in an in vitro breast cancer model." (PMID 32563270, 2020). "HOTAIR is oncogenic and miR-204 is a tumor suppressor, accordingly they showed high and low expression in breast carcinoma, respectively, and dictate low overall survival and poor prognosis." (PMID 32466537, 2020). "More recent studies showed that HOTAIR can be transcriptionally induced upon hypoxic conditions also in other tumor types, including colon cancer, breast cancer, cervical cancer, and neuroblastoma cells." (PMID 31072041, 2019). "Studies also suggest that HOTAIR is involved in the epithelial to mesenchymal transition (EMT) in breast cancer and associated with maintenance of stemness of breast cancer cells." (PMID 31882666, 2019).